IL10 (interleukin 10)
Diseases named in the same sentence as IL10 in open-access papers (continued):
Sharing a sentence is not in itself a finding about the gene and the disease.
bacterial infection (continued). "In turn, during bacterial infection, we observed higher upregulation of the expression of inos, il-12p35, ifnγ-2, arginase 2 and il-10 in the liver of carp sampled in spring." (PMID 38157099, 2024). "Activation of the IFN-γ signaling pathway can decrease IL-10, metanephrine, and normetanephrine in blood circulation, improve lymphocyte function, and reduce bacterial infection." (PMID 39877656, 2024). "Meanwhile, cytokine genes such as IL2, IL10, and IL15, associated with innate immunity against bacterial infection, mostly showed positive correlations in the GI immune-related tissues of infected animals." (PMID 38563680, 2024). "IL-10 inhibits antibacterial defenses, and treatment of IAV-infected mice with anti-IL-10 antibodies can improve survival rates from secondary bacterial infection." (PMID 38138118, 2023). "It is worth noting that IL-10 has well-defined roles in mediating the pathogenesis of bacterial infections due to its broad immunosuppressive effects." (PMID 36835169, 2023). "The results suggested that a large sputum volume, a higher AAT value, and a lower IL-10 value were significant predictors of bacterial infection." (PMID 37876022, 2023). "Among the JAK family members, TYK2 holds significance in mediating IL-10 dependent signaling as anti-inflammatory responses during bacterial infections." (PMID 37808912, 2023). "Single-cell transcriptional analysis revealed that PB-PCs from active-disease mice exhibited increased expression of inflammatory pathway genes, which differed from IL-10 producing PB-PCs induced in a normal immune response to bacterial infection." (PMID 38155972, 2023). "To achieve this, we analyzed publicly available bulk gene expression data from a population of IL-10 producing PB-PCs induced in response to bacterial infection." (PMID 38155972, 2023). "Because PPARγ has been shown to regulate IL-10 production during bacterial infection, we found that cadmium exposure and S. pneumoniae infection reduced IL-10 levels in the Pparfl/fl mice, and the PpargΔM mice showed an even greater reduction." (PMID 36928191, 2023). "Gene Set Enrichment Analysis indicated that bacterial infection was associated with upregulation of IFNβ, ISG15, and IL10." (PMID 37876725, 2023). "The results indicated that AAT/IL-10 ratio was more discriminative of bacterial infection than AAT and IL-10 alone." (PMID 37876022, 2023). "This suggests that serum levels of IL-6 and IL-10 can rapidly discern between G + and G- bacterial infections, thereby offering valuable guidance to clinicians for prompt and suitable administration of antibiotic therapy." (PMID 37986183, 2023). "A previous study has highlighted the potential of IL-6 and IL-10 as markers to differentiate between G- and G + bacterial infections in children with hematological disorders who have BSI." (PMID 37986183, 2023). "The levels of cytokines, especially IL-6 and IL-10, usually increase during bacterial infection and are considered to represent early biomarkers to assist in the diagnosis of bacterial infections." (PMID 37953798, 2023). "Researchers discovered that ADRB2 signaling synergizes with Toll receptors to promote rapid IL-10 release, but ADRB2 deficiency results in inflammation in bacterial infections and inflammatory colitis." (PMID 38011291, 2023). "In the NPMODS subgroup, however, only IL-10 exhibited statistical differences between G+ and G- bacterial infection (p < 0.005), while IL-6 was significantly elevated regardless of bacterial Gram type." (PMID 36544765, 2022). "This was consistent with a previous perspective stating that IL-10 was the most useful predictor for G- bacterial infection in critically-ill sepsis patients." (PMID 36544765, 2022). "The prominent liver IFN signature and myeloid cells with increased IL-10 production after bacterial infection was also found in patients with liver cirrhosis." (PMID 36052075, 2022).
bacterial infection (continued). "Cytokines associated with bacterial infections were downregulated (i.e., IL1β, IL6, IL8, TNFα), whereas the anti-inflammatory cytokine IL10 was upregulated." (PMID 36671404, 2022). "In many protozoan and bacterial infections, the role of IL-10 in limiting IFNγ expression is critical for host survival, suppressing damaging immunopathology." (PMID 35428872, 2022). "The specificity and sensitivity of using IL-6 combined with the IL-10 cytokine to identify G- and G+ bacterial infections were both greater than 80%." (PMID 35432366, 2022). "These discrepancies suggest that IL-10 and IL-4 signaling are differently regulated in response to bacterial infection versus tissue injury or reflect interspecies differences." (PMID 36127326, 2022). "IL-10 plays a key role in the context of acute bacterial infection of the intestine in preventing excessive inflammation by limiting innate immunity." (PMID 34239502, 2021). "The Treg-mediated release of elevated IL-10, designed to modulate to the pro-inflammatory response to the declining bacterial infection, impaired the patient’s T-cell-mediated immune response to emergent SNV effectively." (PMID 34452463, 2021). "Intranasal administration of recombinant IL-10 rescued mice from the lethality of the bacterial infection by promoting bacterial clearance and reducing production of cytokines and chemokines in the lungs." (PMID 32153580, 2020). "The interplay between IL-10, IL-12p40, and IL-6 intense affected the outcomes of macrophage function and bacterial infection." (PMID 32117813, 2020). "While a significant up-regulation of IL-10 was seen in the late stage of bacterial infection, indicating OnGal8-L can regulate inflammation response in vivo during bacterial infection." (PMID 32676073, 2020). "Interleukin-10 plays important, yet contrasting, roles in host protection against bacterial infections and in the septic response." (PMID 32153580, 2020). "In the present study, we support a role for IL-10 induced by MAP protein through immune networks during bacterial infection." (PMID 32290379, 2020). "Rather, it is due to Plasmodium-induced hemolysis, and subsequent activation of HO-1 and IL-10 that inhibit neutrophil functions lead to weakened immune responses to invasive bacterial infections." (PMID 32714882, 2020). "This prolonged IFN-I and virally induced IL-10 set the scene for secondary bacterial infection, which can add a strong IL1β and TNFα-mediated inflammatory response to magnify lung damage." (PMID 32595654, 2020). "IL-10 exerts both harmful and beneficial effects in host defenses against bacterial infections, depending on their strains." (PMID 32153580, 2020). "Our results show that the co-treatment of PBMCs with rbIFN-λ and LPS reduced IL-10 levels compared to LPS alone, which can modulate inflammation produced by bacterial infections." (PMID 33240967, 2020). "Cytokines such as TNF-α, KC, IL-1β, and IL-10, released, among others, by PMNs, orchestrate the innate immune response in bacterial infections." (PMID 33613460, 2020). "Taken together, it is likely that IL-10 is involved in host defenses against bacterial infections with various phenotypes and mechanisms, depending on the bacterial species." (PMID 32153580, 2020). "In the last years, increasing data support the idea that IL-10 production drives the development of a successful immune response during bacterial infection." (PMID 30279680, 2018). "Conversely, for MDR bacterial infection, IL-10 impairs host survival and bacterial clearance during intracellular and/or weak pro-inflammatory bacteria." (PMID 30279680, 2018). "In the previous section, we described that the production of IL-10 plays a critical role during MDR-bacterial infections." (PMID 30279680, 2018). "IL-22, a member of the IL-10 cytokine family, has been demonstrated to play an important role in mucosal immunity in protecting bacterial infections and regulating microbiota in the gut." (PMID 29329335, 2018).
bacterial infection (continued). "Remarkably, infiltrating CD11b+Ly6G+ neutrophils have been identified as the main producers of IL-10 during systematic bacterial infections." (PMID 29953538, 2018). "Interleukin-10 (IL-10) is one of the most important anti-inflammatory cytokine produced during bacterial infection." (PMID 30279680, 2018). "These clearly confirm the suppressive role of IL-10 in naïve T cell priming during bacterial infection." (PMID 30233599, 2018). "IL‐10 is an immunosuppressive cytokine that is normally up‐regulated in inflamed pulp by bacterial infection to prevent the spread of inflammation." (PMID 29316223, 2018). "In bacterial infections, IL-10 is readily produced by cells from the innate immune system upon recognition of several pathogen-associated molecular patterns (PAMPs)." (PMID 28824622, 2017). "During bacterial infection, IL-10 down-regulates Th1 by suppressing overexpressed immunopathology associated factors, such as IFN-γ and TNF-α, and subsequently preventing multiple severe immune responses." (PMID 29340060, 2017). "Studies have been done using IL-10 expression to examine the host immune response to bacterial infection." (PMID 28424669, 2017). "Although IL-10 is primarily recognized for its anti-inflammatory properties, this cytokine can have either favorable or unfavorable effects on the host depending on the nature of the bacterial infection or the levels of IL-10 produced." (PMID 29202047, 2017). "Many bacterial infections induce overexpression of IL-10, which is leading to uncontrolled pathogen growth." (PMID 28915878, 2017). "Previous studies have shown that melatonin suppresses TNF-α, IL-1β, IL-6, IL-8, and IL-10 during bacterial infections or LPS treatment in vitro and in vivo." (PMID 28542575, 2017). "Chronic TLR4 activation in bacterial infection with persistent lipopolysaccharide produces anti-inflammatory IL10, and in Aspergillus sp." (PMID 28573109, 2017). "The key finding in our study is the ability of cardiolipin to inhibit anti-inflammatory mechanisms such as IL-10 production from lung MDSCs, which is the principal source of IL-10 during bacterial infection." (PMID 28074841, 2017). "As they suggested, the AUC demonstrated the best discriminatory power for IL-10 and showed the highest sensitivity for detecting bacterial infections in this study." (PMID 28148470, 2017). "High levels of interleukin-10 prevent the release of pro-inflammatory cytokines tumor necrosis factor α and interleukin-1β which allow the bacterial infection in the mammary glands to remain dormant." (PMID 28542500, 2017). "IL-10 limits auto-inflammatory responses, but over-vigorous IL-10 production early during bacterial infection can be detrimental to the host by suppressing inflammation necessary to clear bacteria." (PMID 27434537, 2016). "IL-2, IL-10, and tumor necrosis factor (TNF) alpha showed weak diagnostic performance in distinguishing between bacterial and non-bacterial infections." (PMID 27486746, 2016). "Although the present study suggests that aged mice have a heightened innate immune response to bacterial infection, several questions regarding the role of IL-10 in this process, and the functional capacity of aged neutrophils, remain." (PMID 25595646, 2015). "After LPS stimulation, the expression of frog IL-10 was upregulated greatly in the tissues, including liver, spleen, kidney, intestine, and stomach, indicating that frog IL-10 should act an important role for resistance against bacterial infections." (PMID 25759841, 2015). "The frog IL-10 mRNA was upregulated at 24 h after LPS stimulation, indicating that it plays a part in the host immune response to bacterial infection." (PMID 25759841, 2015). "It is possible that DnaK acts as an immunomodulator with a putative virulence role in bacterial infections, polarizing macrophages to M2, with production of IL-10." (PMID 25419575, 2014).
bacterial infection (continued). "Mouse Ly6C+ monocytes have a high antimicrobial capability due to their potent capacity for phagocytosis, secrete ROS, TNFα, nitric oxide, IL-1β, little IL-10 upon bacterial infection and large amount of type 1 interferon (IFN) in response to viral ligands." (PMID 24398220, 2014). "Despite apparent differences, no statistical difference was reached, suggesting a rather uniform IL-10 secretion after bacterial infection." (PMID 24223777, 2013). "Lymphocytopenia, IL-10 and IL-6 concentrations on day 1 as well as noradrenalin and normetanephrin levels were highly correlated to the subsequent development of bacterial infections." (PMID 24069356, 2013). "The bacterial infection induced a colonic mucosal IL-10-driven anti-inflammatory response as well as an effector response characterized by the production of IL-17 and MCP-1 in wild-type mice." (PMID 23071818, 2012). "There was, however, a significantly higher level of IL-10 expression following BHV-1 infection in animals that died following secondary bacterial infection." (PMID 22435642, 2012). "As shown here, the GBS GAPDH induced host IL-10 production detected early after bacterial infection." (PMID 22114550, 2011). "IL-12 is a proinflammatory cytokine known to elicit a T-lymphocyte–mediatedimmune response against bacterial infection, whereas IL-10 is an antiinflammatory cytokine known to prolong the survivalof intracellular pathogens in AM." (PMID 16882535, 2006). "Although there was a significant reduction in IL‐10 levels in IL‐6‐deficient mice, this did not alter susceptibility to secondary bacterial infection." (PMID 39921246, 2025). "For example, in fish, IL-10 and IL-20L may play a role in the host’s late-stage reaction to bacterial infection, which differs from the expression pattern in mammals." (PMID 41300695, 2025). "Interleukin-10 acts as a feedback regulator of these Th1 immune responses by suppressing IL-12 production, while at the same time controlling inflammatory responses during bacterial infections." (PMID 41130048, 2025). "There are numerous cellular targets of IL-10 during bacterial infection." (PMID 37381945, 2024). "Accordingly, in the presence of ceragenins, the observed decrease in IL-10 may indicate a transition in the immune response to a more pro-inflammatory state, which could potentially improve the host’s capacity to combat the bacterial infection." (PMID 39598357, 2024). "Global IFNLR1-/- mice in our study had decreased IL-10 6 hours post bacterial infection compared to WT mice, indicating that IL-10 production or lack thereof in IFNLR1-/- mice may also contribute to increased IL-17 levels in the lung." (PMID 39178311, 2024). "This suggests that the bacterial infection induced strong inflammatory responses and is combined with the inability of the fish to come out of this state by producing anti-inflammatory cytokines (il-10 and tgf-β)." (PMID 36838503, 2023). "Of these, only IL10 exhibited association with immunosuppressive effects, indicating that the IFNβ-IL10 network is likely involved in regulating immune response to bacterial infection, while IL10 production is responsible for the immunosuppressive effect of the IFNβ-IL10 network." (PMID 37876725, 2023). "The anti-inflammatory cytokine IL-10, which is secreted by microglia in response to bacterial infection may also be responsible for tuning the CNS inflammatory milieu and ensuring neuroprotection." (PMID 37983247, 2023). "In other words, AAT and IL-10 were inversely correlated in terms of predicting bacterial infection." (PMID 37876022, 2023). "Moreover, GSEA identified IFNAR1, ISG15 and IL10 as potential regulators of both bacterial infection and immune response." (PMID 37876725, 2023). "Thus, our results, together with other researches, demonstrating that IL-10 plays an important role in protecting the host from bacterial infection." (PMID 37443161, 2023).
bacterial infection (continued). "Additionally, it is also noteworthy that HPV infection modulates the immunological response towards a predominance of Th2-type response (IL-4, IL-5, IL-10, and IL-13), which favors persistence of bacterial infection." (PMID 36897879, 2023). "Notably, both ISG15 and IL10 play a crucial role in the innate immune response to viral or microbial infections, and the ISG15/IL-10 axis has been shown to exert an anti-inflammatory effect in bacterial infections as well." (PMID 37876725, 2023). "First, bacterial infection can augment the autoimmune response: Streptococcus combined with Veillonella isolated from the human small intestine microbiota inhibited IL-12p70 production and augmented IL-8, IL-6, IL-10 and TNF-α responses." (PMID 35847775, 2022). "Therefore, this study believes that the levels of IL-6 and IL-10 can roughly determine G-/G+ bacterial infection." (PMID 35432366, 2022). "Differentiation of G-/G+ bacterial infections with IL-6 combined with IL-10." (PMID 35432366, 2022). "Therefore, we further studied the combination of IL-6 and IL-10 to identify G-/G+ bacterial infections." (PMID 35432366, 2022). "Some scholars even found that IL-6/IL-10 could be used to identify G-/G+ bacterial infections in children." (PMID 35432366, 2022). "In addition, STAT3 is involved in regulating the body’s response to viral and bacterial infections since the interaction of IL-6 and IL-10 with their respective receptors triggers the phosphorylation process of STAT3." (PMID 35327350, 2022). "It should be noted that the abnormal increase of IL-6, IL-8 and IL-10 in patients with hematological malignancies may not only occur when bacterial infections in the lungs occur." (PMID 34925324, 2021). "Production of IL-10 is more destructive to the host in case of intracellular bacterial infections." (PMID 33488991, 2021). "It was also reported that in mice model, the secretion of IL-10 induced by the influenza virus reduced the clearance of S. pneumoniae by NK cells, and that the use of an antibody against IL-10 reduced the mortality to a secondary bacterial infection." (PMID 32997525, 2021). "In adult patients with hematological malignancies with bacterial infection of the lungs, as an anti-inflammatory factor, the increase of IL-10 may be to inhibit the high expression of the pro-inflammatory factors IL-6 and IL-8." (PMID 34925324, 2021). "Furthermore, lipopolysaccharide-induced TLR4 signaling cascades were shown to repress the expression of the let-7 family and rescue cytokine production of IL-6 and IL-10, both of which are critical in bacterial infection." (PMID 33805523, 2021). "The balance of anti-inflammatory (IL-10) and proinflammatory (IL-12, IF-g, and IL-6) cytokines modulates the composition and the maturation of the phagosome (phagosome conversion) in its fusion with the lysosome during the bacterial infection process." (PMID 34356768, 2021). "Since S. pneumoniae induces a high influx of neutrophils into the lungs that subsequently would produce IL-10, this could be a host mechanism to prevent inflammatory damage activated by bacterial infection." (PMID 33995357, 2021). "Elevated level of IL-10 in the blood may have a pivotal role in controlling inadequate inflammation, typically observed in the course of uncontrolled bacterial infections." (PMID 33237133, 2020). "During bacterial infection, the antibiotic effect of IL-10 appears to be completely different." (PMID 32974363, 2020). "In the case of ASFV, it is plausible to speculate that several cellular subsets might be involved in an aberrant immune response in which IL-10 plays a central role, as it has been shown in bacterial infections." (PMID 32376618, 2020). "IL-10 acts as an anti-inflammatory cytokine in bacterial infections." (PMID 32460745, 2020). "Mast cells are a major source of IL-10 in the bladder following bacterial infection." (PMID 32821646, 2020).